RN7SL346P (RNA, 7SL, cytoplasmic 346, pseudogene)
Gene: Miscellaneous RNA gene on chromosome 15 (90,166,233 to 90,166,526, forward strand). Ensembl gene ENSG00000240470.
Homologues: Orthologues: chimpanzee Metazoa_SRP (98% identical), macaque Metazoa_SRP (90% identical). Paralogues in human: RN7SL2 (82% identical), RN7SL1 (82% identical), RN7SL3 (81% identical), RN7SL444P (78% identical), RN7SL220P (78% identical), RN7SL664P (78% identical), RN7SL711P (78% identical), RN7SL804P (78% identical), RN7SL88P (78% identical), RN7SL147P (78% identical), RN7SL18P (78% identical), RN7SL296P (78% identical), and 701 more.